DPY19L3 (dpy-19 like C-mannosyltransferase 3)
Description:
C-mannosyltransferase that mediates C-mannosylation of tryptophan residues on target proteins. The reaction occurs on the luminal side of the endoplasmic reticulum and involves the transfer of a mannose unit from a dolichylphosphate mannose (Dol-P-Man) donor to an acceptor protein containing a WxxW or WxxC consensus sequence. C-mannosylates RSPO1, a Wnt signaling regulator, preferentially at the first Trp residue in the sequence WxxW. C-mannosylates the netrin receptor UNC5A, preferentially at the third tryptophan of WxxWxxWxxC sequence (By similarity). [Isoform 2]: Has no C-mannosyltransferase activity.
Tractability: Antibody: UniProt predicts a signal peptide or a membrane-spanning region. PROTAC: its protein half-life has been measured.
Gene: Protein-coding gene on chromosome 19 (32,405,543 to 32,485,895, forward strand). Ensembl gene ENSG00000178904.
Subcellular location: Endoplasmic reticulum membrane; Endoplasmic reticulum membrane (Isoform 2)
Subcellular location (Human Protein Atlas): Microtubules
Gene Ontology:
Molecular function: mannosyltransferase activity
Cellular component: endoplasmic reticulum membrane; membrane
Genetic constraint (gnomAD): Loss-of-function variants: 37 observed, 72.29 expected, observed/expected ratio (o/e) 0.51, 90% interval 0.39 to 0.67. The upper end of that interval is the gene's LOEUF score, 0.67, which puts it in group 2 of 6, group 1 being the genes least tolerant of losing a copy. Missense variants: 570 observed, 738.29 expected, observed/expected ratio (o/e) 0.77, 90% interval 0.72 to 0.83. Synonymous variants: 258 observed, 280.17 expected, observed/expected ratio (o/e) 0.92, 90% interval 0.83 to 1.02.
Homologues: Orthologues: chimpanzee DPY19L3 (99% identical), macaque DPY19L3 (99% identical), rabbit DPY19L3 (94% identical), pig DPY19L3 (93% identical), dog DPY19L3 (93% identical), guinea pig DPY19L3 (93% identical), rat Dpy19l3 (88% identical), mouse Dpy19l3 (88% identical), tropical clawed frog dpy19l3 (67% identical), zebrafish dpy19l3 (62% identical), Drosophila melanogaster CG6659 (22% identical). Paralogues in human: DPY19L4 (43% identical), DPY19L1 (30% identical), DPY19L2 (28% identical).
Diseases named in the same sentence as DPY19L3 in open-access papers:
DPY19L3 is named in the same sentence as 6 diseases in open-access papers, as found by Europe PMC text mining. Sharing a sentence is not in itself a finding about the gene and the disease. The quoted sentences say what the papers report.
bipolar disorder (1 paper, 2017). A disorder of the brain that causes unusual shifts in mood, energy, activity levels and the ability to carry out day-to-day tasks. "Sequence variation in the Dpy19l3 (Dpy-19-like C-mannosyltransferase 3) gene has been suggested to contribute to bipolar disorder." (PMID 29403433, 2017).
breast carcinoma (1 paper, 2024). "Moreover, knockdown (KD) of DPY19L3 decreased VM capability in MDA-MB-231 human breast cancer cells, suggesting that DPY19L3-mediated C-mannosylated proteins regulate these phenomena and that DPY19L3 is a new molecular target for cancer therapy." (PMID 38560568, 2024). "To broaden our study, we centered our attention on the function of DPY19L3 in breast cancer." (PMID 38560568, 2024).
fibrosarcoma (1 paper, 2024). A malignant mesenchymal fibroblastic neoplasm affecting the soft tissue and bone. "Knockout of DPY19L3 inhibited the formation of VM in HT1080 human fibrosarcoma cells." (PMID 38560568, 2024). "Knockout (KO) of DPY19L3 gene resulted in suppression of both VM and proliferation in HT1080 human fibrosarcoma cells." (PMID 38560568, 2024).
ocular coloboma (1 paper, 2021). "We observed that targeting of dpy19l3 partially caused defects in optic fissure fusion, called coloboma." (PMID 33975020, 2021). "Interestingly, dpy19l3 crispant medaka embryos partially developed ocular coloboma, that is a gap caused by incomplete closure of the optic fissure." (PMID 33975020, 2021). "•Targeting of dpy19l3 in medaka occasionally led to coloboma." (PMID 33975020, 2021).
cancer (1 paper, 2024). A tumor composed of atypical neoplastic, often pleomorphic cells that invade other tissues. "In summary, DPY19L3-mediated C-mannosylation is a novel auspicious cancer molecular target, as our results suggest." (PMID 38560568, 2024).
tumor (1 paper, 2026). "Furthermore, changes in the transcriptional expression of C-Man-Trp metabolism-related genes, C-mannosyltransferases (Dpy19l1 and Dpy19l3), and thrombospondin type I repeat superfamily genes (Thbs1, Spon1, and cellular communication network factor 1) were noted in tumor-associated cells and tissues." (PMID 41812877, 2026).